VDAC1 (voltage dependent anion channel 1)
Diseases named in the same sentence as VDAC1 in open-access papers (continued):
Sharing a sentence is not in itself a finding about the gene and the disease.
pancreatic cancer (13 papers, 2016 to 2026). "Loss of the VDAC isoform VDAC1 leads to ATP depletion, which results in decreased cell growth and migration in colon, lung and pancreatic cancer cells both in vitro and in vivo." (PMID 34070562, 2021). "Collectively, this study provides a genomic alteration-informed multiomics framework supporting VDAC1 as a mitochondrial-associated biomarker in PDAC and highlights its potential relevance for molecular characterization of pancreatic cancer." (PMID 42111501, 2026). "Functional validation demonstrated that VDAC1 silencing impaired pancreatic cancer cell proliferation and disrupted mitochondrial homeostasis, including reduced mitochondrial membrane potential, ATP production, and mitochondrial reactive oxygen species levels." (PMID 42111501, 2026). "In carcinoma cells of prostate epithelial cells, a reduced pl-VDAC-1 expression was reported, while an increased pl-VDAC-1 expression was found in human pancreatic carcinoma cells." (PMID 38474278, 2024). "VDAC1 mRNA and protein were detected in 9 paired human pancreatic cancer tissues and normal pancreas (clinical characteristics in supplement)." (PMID 27659305, 2016). "VDAC1 silencing with RNAi significantly decreased cell growth, invasion and migration in the pancreatic cancer cell line Capan-1." (PMID 27659305, 2016). "Results showed that VDAC1 mRNA and protein expression level in pancreatic cancer tissue were significant increased compared to normal pancreas samples respectively." (PMID 27659305, 2016). "Further studies focusing on VDAC1 demonstrated that VDAC1 mRNA and protein were significantly expressed in the tested pancreatic cancer cell lines." (PMID 27659305, 2016). "To investigate the biological function of the VDAC1 protein in pancreatic cancer, we firstly detected its expression in eight pancreatic cancer cell lines." (PMID 27659305, 2016). "Additionally, the usefulness of a three-gene signature (PRKN, SRC and VDAC1) was evaluated based on genes related to mitophagy to predict survival in pancreatic cancer patients." (PMID 38048216, 2023). "VDAC1 played a role in modulating malignant phenotype in pancreatic cancer cells, could serve as a prognostic predictor and a candidate for targeted therapy against pancreatic cancer." (PMID 27659305, 2016). "In summary, we identified VDAC1 as a candidate immunogenic membrane antigen of pancreatic cancer." (PMID 27659305, 2016). "Furthermore, we conducted biological function experiments to down regulate VDAC1 protein levels in the human pancreatic cancer cell line Capan-1 using transient transfection." (PMID 27659305, 2016). "Additionally, VDAC1 expression was upregulated in pancreatic cancer tissue compared with normal pancreas samples and patients with low VDAC1 expression had a significantly greater median survival compared to those with high expression (27.0 months vs. 17.8 months, P = 0.039)." (PMID 27659305, 2016). "Other candidate background-specific trigenic interactions include the VDAC1/2/3 voltage-gated anion channel family and the ME1/2/3 malic enzyme family, two of which were previously shown to be synthetic lethal in pancreatic cancer under nutrient limiting conditions." (PMID 38678031, 2024).
COVID-19 (12 papers, 2021 to 2025). A disease caused by infection with severe acute respiratory syndrome coronavirus 2. "In the immune cell metabolism program of COVID-19 patients, voltage-dependent anion channel 1 (VDAC1) was expressed in the T cell population, which is associated with mitochondrial dysfunction and apoptosis." (PMID 35185933, 2022). "A highly expressed voltage-dependent anion channel 1, a mitochondrial membrane protein for transporting calcium, was suggested as a cause of mitochondrial dysregulation and apoptosis of T cells in COVID-19 patients." (PMID 35095881, 2021). "In severe COVID-19 patients, the mitochondria were irregularly shaped, and cytochrome c was found in the cytosol (subsequently inducing apoptosis), suggesting that high VDAC1 expression makes these T cells more susceptible to death." (PMID 38390960, 2024). "Based on recent findings demonstrating that fmtDNA is released from the mitochondria via oligomeric VDAC1, we suggest that a similar mechanism would be applied in COVID-19." (PMID 39375263, 2024). "Another study on T-cells unique to acute COVID-19 patients revealed the upregulation of metabolic protein VDAC1 (voltage dependent anion channel 1) and H3K27me3, which is a major histone modification marking transcriptional repression." (PMID 38390960, 2024). "A distinct population of T cells in COVID-19 patients exhibits significant upregulation of VDAC1 and VDAC1-dependent apoptosis that can be inhibited by VBIT-4." (PMID 39375263, 2024). "The connection of mitochondria and VDAC1 to the metformin effects on cell function presented above has also been demonstrated for COVID-19." (PMID 34671273, 2021). "Here, as mitochondria dysfunction by viruses often involves modulation of VDAC1 expression levels or its activity via the interaction of their specific proteins with VDAC1, we aimed to elucidate the role of VDAC1 in COVID-19 pathology." (PMID 39375263, 2024). "Additionally, we demonstrated that the E-protein of COVID-19 enhances the overexpression and oligomerization of VDAC1, which leads to cell death." (PMID 39375263, 2024). "Myocardia of humans and rats and T cells of COVID-19 patients express increased VDAC1 levels." (PMID 36578022, 2022). "Adding the percentage of VDAC1+CPT1a+ myeloid cells, pDCs, and H3K27Me3+VDAC1+CD4+ improved prediction of COVID-19 severity compared with basic clinical information, highlighting the important contribution of the immune cell populations identified to disease severity." (PMID 33691089, 2021). "Thus, despite similar levels of H3K27Me3 and VDAC1 expression, the expression of proteins involved in metabolic programming of these cells is distinct between severe COVID-A patients and mild COVID-19/COVID-R or hospitalized influenza patients, all of whom recovered." (PMID 33691089, 2021). "We investigated the role of VDAC1 in the pathogenesis of SARS-CoV-2, which manifests as COVID-19." (PMID 39375263, 2024). "The link between VDAC1 and SARS-CoV-2 was demonstrated, by the overexpression of VDAC1 in a population of T cells, suppression of mtDNA release, cGAS-STING pathway activation and improved survival in the T cells of COVID-19 patients when treated with the VDAC1-interacting compound VBIT-4." (PMID 39375263, 2024). "In another study, CPT1a+VDAC1+HLA-DR− M-MDSC frequencies were found to be significantly higher in severe compared to mild COVID-19 patients, and these differences were observed before the respiratory nadir in severe COVID-19 patients." (PMID 38257728, 2023). "Along these lines, the fact that VBIT-4, the inhibitor of VDAC1 aggregation, promotes survival in the T cells from the COVID-19 patients, but not healthy controls, supports a role for VDAC1 in promoting cell death." (PMID 33691089, 2021). "In addition, COVID-19 patients’ T-cells underwent apoptosis that was inhibited by VBIT-4, a compound that targets VDAC1 oligomerization and prevents apoptosis." (PMID 34671273, 2021).
COVID-19 (continued). "Additionally, VDAC1 levels were found to be decreased in extracellular vesicle isolated from the blood of acutely infected patients but not in those with long COVID-19." (PMID 39375263, 2024).
triple-negative breast carcinoma (11 papers, 2017 to 2024). An invasive breast carcinoma which is negative for expression of estrogen receptor (ER), progesterone receptor (PR), and human epidermal growth factor receptor 2 (HER2). "This study suggests that mitochondrial metabolism can be exploited by targeting the DYNLT1-Parkin-VDAC1 axis to improve the ability of metabolic inhibitors to suppress cancers with limited treatment options, such as triple-negative breast cancer (TNBC)." (PMID 37280526, 2023). "As triple-negative breast cancer (TNBC) is a special molecular subtype of HER2-negative breast cancer, which is defined by the absence of the ER, PR, and HER2 genes, with no standard treatment at present, we then explored the correlation of VDAC1 expression with the prognosis of TNBC." (PMID 33680287, 2021).
type 2 diabetes (11 papers, 2017 to 2025). "In type 2 diabetes, VDAC1 is overexpressed in pancreatic β‐cells and is linked to impaired cellular ATP generation, both of which may contribute to β‐cell dysfunction and insulin resistance." (PMID 40285415, 2025). "Moreover, we have shown that VBIT-4 or VBIT-12 prevents mitochondrial dysfunction and apoptosis in several mouse models of diseases that show VDAC1 overexpression, such as type 2 diabetes (T2D), lupus, and colitis." (PMID 36578022, 2022). "Here, we demonstrate that the VDAC1-based peptide, R-Tf-D-LP4, affects several parameters of a NAFLD mouse model in which administration of streptozotocin (STZ) and high-fat diet 32 (STZ/HFD-32) led to both type 2 diabetes (T2D) and NAFLD phenotypes." (PMID 32093016, 2020).
ovarian carcinoma (10 papers, 2019 to 2025). A malignant neoplasm originating from the surface ovarian epithelium. "In addition, PGC1α promoted cisplatin resistance by modulating the HSP70/HK2/VDAC1 signaling pathway, affecting the binding of HK2 to VDAC1, causing alterations in mitochondrial membrane potential, and reducing the apoptosis of ovarian cancer cells." (PMID 38711526, 2024). "VDAC1 (Voltage Dependent Anion Channel 1) was shown to play a critical role in promoting cisplatin resistance in ovarian cancer by regulating the HSP70/HK2/VDAC1 signaling pathway." (PMID 38038814, 2023). "We found that after infection with shPGC1α and the simultaneous addition of cisplatin, the mitochondrial localization of HK2 and the binding of HK2 and VDAC1 in ovarian cancer drug-resistant cells decreased and apoptosis increased." (PMID 33802591, 2021). "The upregulation of VDAC1 mediated by the overexpression of PGC1α along with HSP70 was found to result in the increased glycolysis and reduced mitochondrial function in ovarian cancer cells; indicating the potential of VDAC1 as a therapeutic target in ovarian cancer." (PMID 38038814, 2023). "Furthermore, HSP70 induces the expression of HK2 in mitochondria and its binding with VDAC1, consequently promoting cisplatin resistance in ovarian cancer." (PMID 33802591, 2021). "Based on these results, PGC1α may reduce apoptosis through the HSP70/HK2/VDAC1 signaling pathway, thus promoting cisplatin resistance of ovarian cancer." (PMID 33802591, 2021). "Thus, PGC1α may act on mitochondria to regulate the HSP70/HK2/VDAC1 signaling pathway and reduce apoptosis, promoting cisplatin resistance in ovarian cancer." (PMID 38711526, 2024). "Therefore, PGC1α may promote cisplatin sensitivity of ovarian cancer cells through the HSP70/HK2/VDAC1 signaling pathway." (PMID 33802591, 2021). "Validation of VDAC1 and LDLRAP1 in clinical trials is needed before off-label use of statins in ovarian cancer can be considered." (PMID 40807057, 2025). "To confirm this result, we evaluated VDAC1 and LDLRAP1 expression in each of the existing cell lines and human ovarian cancer ascites-derived cell lines." (PMID 35215239, 2022). "Although the mechanisms by which VDAC1 and LDLRAP1 are involved in statin response remain to be elucidated, clinical trials in which the expression of these genes narrows down the cases of ovarian cancer will be very promising." (PMID 35215239, 2022).
Hyperglycemia (9 papers, 2017 to 2024). An increased concentration of glucose in the blood. "In response to hyperglycemia, the mRNA level of VDAC1 increased in endotheliocytes and decreased in human skin fibroblasts." (PMID 37507997, 2023). "In the next part of the work, we investigated how the decrease in VDAC1 gene expression in primary human skin fibroblasts affects hyperglycemia-induced mitochondrial damage." (PMID 37507997, 2023). "The present work aims to study the molecular mechanisms of hyperglycemia-mediated mitochondrial dysfunction and its regulation through pharmacological and genetic suppression of VDAC1 activity in primary endotheliocyte and fibroblast cell cultures." (PMID 37507997, 2023). "At the same time, the relative decrease in calcein fluorescence induced by hyperglycemia in cells with reduced VDAC1 expression was less pronounced (1.18-fold)." (PMID 37507997, 2023). "Under conditions of hyperglycemia, cells with reduced expression of VDAC1 demonstrate less dysfunctional changes in the mitochondrial membrane potential, H2O2 generation rate, and spontaneous activity of MPT pore opening compared to control fibroblasts." (PMID 37507997, 2023). "Hyperglycemia induced an increase in the expression of the Vdac1 gene in endothelial cells, while fibroblasts showed a decrease in the Vdac1 mRNA level." (PMID 37507997, 2023). "It is important to note that these two cell cultures differ in their response in terms of VDAC1 expression to hyperglycemia." (PMID 37507997, 2023). "The aim of this work is to better clarify the role of matrix metalloproteinase 2 (MMP-2) isoforms and of translocator protein (TSPO)/voltage-dependent anion-selective channel 1 (VDAC1) modulation in the development of hyperglycaemia-induced myocardial injury." (PMID 33050121, 2020). "In particular, we have demonstrated that, during the early phase of cardiac injury caused by chronic hyperglycaemia, ventricular dysfunction was associated with a change in the outer mitochondrial membrane, characterized by TSPO and VDAC1 overexpression." (PMID 33050121, 2020). "VDAC1 inhibitors, including metformin, restore insulin secretion in T2D islet donors and prevent hyperglycemia in diabetic mice." (PMID 30293774, 2019). "Treatment of db/db mice with VDAC1 inhibitor prevents hyperglycemia, and maintains normal glucose tolerance and physiological regulation of insulin secretion." (PMID 30293774, 2019). "Therefore, we evaluated the effect of hyperglycemia on changes in Vdac1 gene expression in primary human skin fibroblast cells and mouse microvascular endothelial cells." (PMID 37507997, 2023). "All this may indicate that the decrease in VDAC1 expression may be a protective mechanism under conditions of hyperglycemia." (PMID 37507997, 2023). "VDAC1 overexpression was found to be driven by impaired glycemic levels, and its inhibition restored GSIS and prevented hyperglycemia in db/db mice." (PMID 38891081, 2024). "In this consideration, our study highlights the role of MMP-2 in the regulation of mitochondrial injury mediated by TSPO and VDAC1 in the onset of DCM, thus contributing to the identification of novel potential targets of cardioprotective therapeutic interventions under hyperglycaemia." (PMID 33050121, 2020). "Under hyperglycaemia, increased expression of TSPO and VDAC1 was detected." (PMID 33050121, 2020). "At the same time, according to our results, a change in channel activity (suppression of VDAC oligomerization) or a significant decrease in the expression level of VDAC1 contributes to the normalization of mitochondrial function and prevents cell death during hyperglycemia." (PMID 37507997, 2023). "Moreover, cells with suppressed expression of VDAC1 practically did not lose their viability under conditions of hyperglycemia." (PMID 37507997, 2023).
lung adenocarcinoma (9 papers, 2015 to 2023). A carcinoma that arises from the lung and is characterized by the presence of malignant glandular epithelial cells. "Furthermore, we observed that VDAC1 expression, as a marker for mitochondrial content, is associated with reduced survival in three lung adenocarcinoma datasets." (PMID 36052260, 2022). "When we analyzed VDAC1 expression levels in different datasets of lung adenocarcinomas, we observed that it is higher expressed in tumors than in healthy tissue and is associated with poor survival." (PMID 36052260, 2022). "VDAC1 expression was also correlated with tumor progression and sensitivity to chemotherapy, whereas gene expression or proteomic analysis of NSCLC or primary lung adenocarcinoma patients revealed high VDAC1 expression levels as a predictor of poor outcome." (PMID 27289382, 2016). "We demonstrated previously that VDAC1 was post-translationally C-terminal cleaved not only in various hypoxic cancer cells but also in tumor tissues of patients with lung adenocarcinomas." (PMID 26322231, 2015). "VDAC1 mRNA levels are higher in lung adenocarcinoma than in healthy lung tissue." (PMID 36052260, 2022). "All these results suggested that VDAC1 might serve as a potential prognosis marker in lung adenocarcinoma cases, consistent with the proteomics results of lung adenocarcinoma tissue." (PMID 35958281, 2022). "While we observed more rapid tumor growth of Vdac1−/− RAS MEF compared to Wt RAS MEF, a study using A549 cells (human lung adenocarcinoma epithelial cells) reported that the silencing of Vdac1 expression with siRNA inhibited cancer cell proliferation and tumor growth in vivo." (PMID 26322231, 2015). "The expression of VDAC1 increased in most cancers, and the upregulation of VDAC1 distinctly correlated with the poor prognosis in patients, including breast invasive carcinoma, cervical squamous cell carcinoma, pancreatic adenocarcinoma, lung adenocarcinoma, and skin cutaneous melanoma." (PMID 35958281, 2022). "This study observed a correlation between highly VDAC1 expressed and poor overall survival prognosis of lung adenocarcinoma (P = 0.0015) but not lung squamous cell carcinoma by analyzing the LUSC and LUAD datasets in the TCGA project." (PMID 35958281, 2022). "Furthermore, we performed a group of survival analyses through the Kaplan-Meier plotter approach and observed that high expression of VDAC1 was related to poor OS, FP, and PPS in cases of lung adenocarcinoma." (PMID 35958281, 2022).